CD4 (CD4 molecule)
Diseases named in the same sentence as CD4 in open-access papers (continued):
Sharing a sentence is not in itself a finding about the gene and the disease.
infection (continued). "As increased production of IL-12 was observed in the MLN of N. caninum infected mice, the frequency of CD4+ and CD8+ T cells producing IFN-γ was assessed therein, 4 and 7 days upon infection." (PMID 23937079, 2013). "In contrast to the CD4+ T cell depleted model in which these viruses arose, where a shift towards macrophage targets occurred, CD4+ memory T cells are the principal targets of HIV and SIV in normal infection." (PMID 24219995, 2013). "However, IRF-8−/− mice showed percentages of pulmonary macrophages, DC, CD4+ and CD8+ T cells substantially similar to those of WT-B6 mice, suggesting an accelerated and compensatory pulmonary recruitment of these populations at early stage of infection in deficient animals." (PMID 23717393, 2013). "Immediately prior to infection, human leukocytes were further evaluated in the peripheral blood of BLT mice to determine levels of human T cells, T cell subsets (CD4, CD8), and antigen presenting cells (APC)." (PMID 23691024, 2013). "One month post-infection, a single CCR5-restricted viral cluster was massively distributed in all resting CD4+ subsets from 88% subjects, while one subject showed a slight diversity." (PMID 23691172, 2013). "The presence of BPV in leukocytes was demonstrated, had been observed the BPV presence in peripheral blood mononuclear cells and the presence of L1 protein in CD4+ and CD8+ leukocytes, representing a potential infection sites to BPV-2." (PMID 23956996, 2013). "These high levels of infected cells within the resting CD4 T cell compartment contrast with the low CD4 activation levels we observed among total CD4 T cells, an observation that might question the dogma linking the expression of activation markers to productive infection." (PMID 23691172, 2013). "Our previous studies similarly demonstrate that the numbers of CD4+ Th cells and CD8+ T cells increase in lung between day 7 and 14 after infection." (PMID 23390557, 2013). "CD4+ and CD8+ T cell responses were triggered in the different LNs at 8 days post-infection, as illustrated in ALNs." (PMID 24367519, 2013). "RSV infection significantly increased the absolute numbers in the lungs of IL-17A producing CD4+ T cells, DN T cells, and NKT cells at 2 days post infection." (PMID 24194936, 2013). "TRAIL expression following HIV-1 exposure or infection has been described in T cells, monocytes, and pDC, and TRAIL expressing pDC have been shown to directly induce apoptosis of CD4 T cells in HIV-1 infected patients with high viraemia." (PMID 24455433, 2013). "However, very few cells among the total bulk of HIV DNA+ resting cells can be reactivated to productive infection, and it therefore remains unclear whether latently or productively infected CD4+ T cells are responsible for the largest fraction of CA HIV RNA in patients on ART." (PMID 23587031, 2013). "Based on recent data about T reg expansion during infection, Foxp3 expressing CD4+CD25+ T cells were found responsible for TGF-β and CD4+CD25−Foxp3− T cells for IL-10 production." (PMID 23638195, 2013). "These IFNγ−IL-2+TNFα+ CD4 T cells may be an important target population for vaccination regimens, as these cells are induced upon infection, may have high proliferative potential, and may play a role in providing future effector cells during subsequent infections." (PMID 23526940, 2013). "Nef heightens HIV-1 trans infection by upregulating DC-SIGN expression on DC and promoting DC-T cell clustering, while enhancing activation and proliferation of CD4+ T cells." (PMID 24278768, 2013). "Both Il2 (GFP) and Il21 (mCherry) were predominantly expressed by CD4+ compared to CD8+ T cells and frequencies increased from days 7–15 post infection with low dose LCMV-WE." (PMID 23696736, 2013).
infection (continued). "However, during the course of infection, the co-receptor usage preference of HIV-1 shifts from CCR5 to CXCR4 in 50% of the infected individuals, a change that is frequently associated with the accelerated CD4+ T-cell decline and the rapid progression toward AIDS." (PMID 24312095, 2013). "Both efficacy against infection and efficacy per sporozoite increase with increasing anti-CSP titres and numbers of CSP-specific CD4+ T cells." (PMID 23613845, 2013). "During the first month after infection, IFN-γ producing CD4+ and CD8+ T cells were uniformly present, whereas IL2-producing T cells were very rarely detected." (PMID 24023565, 2013). "Increases in both CD4+ and CD8+ T cell populations were observed at later time points in infection in IKKβ cKO mice." (PMID 23349802, 2013). "As expected from the unaltered CD4 SP cell number and frequency at day 14 after RRV infection in NOD mice, Treg and Teff numbers at this time also were unaffected by RRV infection." (PMID 23554993, 2013). "Overall, CD4+ and CD8+ T cell numbers were increased by RRV infection in NOD mice on days 2 and 6 post infection, BALB/c mice showed evidence of increased numbers on day 6, and T cell numbers were unaltered in C57BL/6 mice." (PMID 23554993, 2013). "The median CD4 cell count 354 cells/mm3 (IQR: 181–540), which indicates that approximately half of the included patients were diagnosed at a stage of their infection where they were eligible to receive antiretroviral treatment." (PMID 23551870, 2013). "It has been previously shown that strong antibody, CD4, and CD8 responses are generated upon infection by v50ΔB13RMγ in spite of the low replication levels in vivo." (PMID 24147092, 2013). "This unique discovery opened a new, non-CD4/coreceptor dependent pathway for HIV-1 cis and trans infection of T cells by passaging through DC." (PMID 24278768, 2013). "For example, disruption of IL-4Rα expression on CD4+ T-cells results in a significantly reduced TH2 response to primary N. brasiliensis infection and contributes to optimal control of secondary infection." (PMID 24204255, 2013). "Inflammatory infiltrates consisted of CD4+ and CD8+ T cells with many macrophages and were similar in tissues from animals examined at 2 or 4 weeks after infection." (PMID 24040287, 2013). "Taken together, our results suggest that besides the CD8+ T-cell population, important in the control of CVL, the CD4+ T-cell subset may also simultaneously contribute to improve the cellular immune response in vaccinated dogs to eliminate the parasites from the challenge infection." (PMID 23189161, 2012). "In the acute DENV-infection, T-helper/T-cytotoxic type-1 cell (Th1/Tc1)-related CCR5 is significantly higher expressed on both CD4 and CD8 T cells." (PMID 22815692, 2012). "In the experiments presented here, we have shown that naïve or total CD4+ T cells from NFATp−/− mice are impaired in their ability to produce IFN-γ and TNF mRNA and protein in response to MTb infection." (PMID 22844476, 2012). "A strong CD4+ proliferative T-cell response was observed at the early stage of infection, and IFN-γ, IL-2, and IL-5 were produced within the first weeks after infection whereas the detection of IL-10 was slightly delayed." (PMID 22400039, 2012). "As before, CD4 TNFα producing cells from uninfected or S. enterica infected mice were mainly CD200R– and decreased during infection." (PMID 22496920, 2012). "At eight weeks post infection, we sacrificed the four LAINefdd- and three LAI-infected mice to determine the levels of CD4+ T cells in tissues." (PMID 22640559, 2012). "An ability to replicate in the setting of severely limited CD4+ targets (e.g., advanced disease or CNS infection) would be a selective advantage for SIV or HIV at various times in the course of a typical infection." (PMID 22830620, 2012).
infection (continued). "After intraperitoneal amastigotes inoculation in wild-type and knockout mice for TNF-α, Nod2, Myd88, iNOS, IL-12p40, IL-18, CD4, CD8 and IFN-γ we found that the latter is crucial for controlling infection by G strain amastigotes." (PMID 22509418, 2012). "In L. infantum-infected BALB/c mice, CD4+CD25+ Foxp3+ cells expanded in a pooled fraction of draining lymph nodes and spleen cells at 7 and 28 days of infection." (PMID 22928057, 2012). "CD4+ T cells isolated on days 5 and 7 post-infection from α-CTLA-4-treated mice secreted significantly more IFN-γ and IL-10 than did CD4+ T cells from control mice." (PMID 22319445, 2012). "CD4 T cells were expected to have less pronounced effects relative to CD8 T cells, as infection of microglia and macrophages, constituting MHC class II-expressing APCs, is relatively sparse compared with oligodendrocytes." (PMID 23237504, 2012). "Differences between model assumptions about CD4 decline and HIV transmissibility over the course of infection explained only a modest amount of the variation in model results." (PMID 22802730, 2012). "Altogether, these data showed that CD4 T cells can control replication, prevent lethal infection, and inhibit the establishment of latency in MHV68 infection." (PMID 23012630, 2012). "The number of CD4 and CD8 T cells in the lung and BAL of IL-7Rα449F and Dmu mice was reduced compared to WT after infection, while TSLPR−/− mice had normal numbers of CD4 and CD8 T cells." (PMID 23189186, 2012). "Presence of αβTCR+, CD4+, and CD8+ T cells have been shown to be important for control of infection with attenuated F. tularensis." (PMID 22428026, 2012). "In both uninfected and S. mansoni infected mice a proportion of CD4 T cells produced TNFα but these cells were primarily CD200R– and decreased upon infection." (PMID 22496920, 2012). "Together these data show that the proinflammatory CD4+ T cell response to DENV-1 is largely multifunctional and lasts a minimum of 6 weeks post-infection." (PMID 22816004, 2012). "Interestingly, endosome acidification inhibitors attenuate infections by CD4-independent HIVs, which are thought to be prototypes of CD4-dependent viruses, suggesting that CD4-independent HIV entry may occur through acidic late endosomes, like many animal retroviruses." (PMID 23304142, 2012). "In parallel, we evaluated the magnitude and activation status of CD4+ and CD8+ T cell populations during the course of infection." (PMID 22912884, 2012). "In classical trans infection, DC-SIGN can act as a receptor that efficiently transfers the virus to CD4+ T lymphocytes." (PMID 22851920, 2012). "DC-mediated infection can also occur in trans, by DCs that bind HTLV-1 and transfer the virus to CD4+ T cells prior to becoming infected themselves." (PMID 23109932, 2012). "SMARTA CD4+ T cells, which have a transgenic TCR specific for an LCMV epitope, were transferred into normal mice followed by infection with LCMV." (PMID 22363608, 2012). "In contrast, activated memory CD4+ T cells (CD4+HLA-DR+CD45RO+), which constitute the majority of activated CD4+ T cells at early stages of the infection, predominantly express CCR5,with relatively lower per-cell density of CXCR4." (PMID 22866173, 2012). "BCG vaccination induced a distinct pattern in the DLN cellular dynamics, with an earlier increase in the numbers of total, CD4+ and CD8+ cells, levels that were maintained during the experimental infection." (PMID 22413022, 2012). "Consistent with previous reports in other models that PD-L1 is also expressed on T cells and is further upregulated during activation, PD-L1 was upregulated on virtually all CD4+ and CD8+ T cells by day 5 of PbA infection in both C57BL/6 and BALB/c mice." (PMID 22319445, 2012).
infection (continued). "Our data further suggest that MHC class I and class II dependent antigen presentation was not substantially altered by ageing, thymectomy or latent MCMV-infection to interfere with activation and expansion of tg CD4+ and CD8+ T cells after VACV-infection." (PMID 22916013, 2012). "Passive transfer of immune splenocytes or purified populations of CD4+ and CD8+ T cells obtained after 4 weeks of infection protect mice against brucellosis." (PMID 22500859, 2012). "The magnitude and breadth of Gag CTL responses correlated with post-infection viremic control, but so did anti-Env Ab, tier-1 NAb, ADCC, ADCVI, and Env-specific CD4+ T-cell effector-memory responses." (PMID 23025660, 2012). "These analyses suggest that during periods of active high-level infection, the majority of SIV DNA in resting CD4+ T cells is turning over very rapidly." (PMID 22496643, 2012). "Infection with human immunodeficiency virus type 1 (HIV-1) is characterised by a gradual and progressive CD4+ T-helper cell depletion." (PMID 22726303, 2012). "However, until the discovery of the α4β7 receptor binding site in the V2 domain of gp120, it was not known how HIV-1 could bypass the vast majority of un-activated CD4+ cells in humoral circulation and target the few activated CD4+ cells that could sustain productive infections." (PMID 22720026, 2012). "Following infection, dendritic cells (DC) carry HSV-1 to the draining lymph nodes for activation of CD4+ and CD8+ T cells." (PMID 22691604, 2012). "As already shown on the NK1.1+/CD3+ cell subset, iNKT cells were mostly CD4+, and the proportion of CD4+ iNKT, and CD4-/CD8- iNKT subsets remained nearly stable after infection." (PMID 22457760, 2012). "Consistent with our findings with WT SIVmac251 infection, we found that the cellular SIV DNA in resting CD4 T cells also reverted back to wild type very rapidly in this animal with high levels of viral replication." (PMID 22496643, 2012). "Although CD4+ T cells are the major target of HIV-1, this infection widely impairs the viability and function of numerous other immune cells." (PMID 22591651, 2012). "At 3 dpi, the level of HIV-1 Vpr+ infection was 5-7-fold higher (P<0.05) than that of HIV-1 Vpr− in PBMCs and CD4+ T-cells, respectively." (PMID 22570689, 2012). "In spite of the apparent lymphocyte local depletion, the total number of CD4+ and CD8+ cells increases moderately (two and one fold, respectively) about the 3rd week of infection." (PMID 22500859, 2012). "In L. donovani-infected BALB/c mice, the number of splenic CD4+ CD127dimCD25+GITR+ T cells expressing higher Foxp3 and IL-10 increased at 21 days of infection." (PMID 22928057, 2012). "After infection with human immunodeficiency virus type 1 (HIV-1), CD4+ T lymphocytes decline in number at a variable rate unless treatment is started with antiretroviral therapy (ART)." (PMID 22879884, 2012). "Along with the proliferative response to infection, there was a notable increase in CD122 expression, which gave evidence of two different CD4+ T cell subsets." (PMID 22272258, 2012). "Infection of rhesus macaques with SIV results in high acute plasma viral loads and rapid depletion of mucosal CD4+ T cells." (PMID 22511950, 2012). "This integrin is expressed at high levels on activated CD4+ T cells in the gut and cervicovaginal mucosa, both representing major sites of HIV replication early in infection." (PMID 22693444, 2012). "Our findings demonstrate that the type of infecting virus modulates the virus-specific B cell response to infection of the respiratory tract in DR1 mice, perhaps via an increase in the proportion of IFN-γ-secreting CD4 T cells." (PMID 22457834, 2012). "In marked contrast, 40 days after infection, larger pools of IFN-γ-producing CD4 T cells were detected responding to SseI and SseJ epitopes rather than flagellin." (PMID 22275869, 2012).
infection (continued). "LPS has been suggested to induce reduced expression of CD4 and CCR5, and to increase production of type I IFNs and release of β-chemokines that reduce infection by CCR5-using, HIV-1 envelope glycoproteins, among other mechanisms for its anti-HIV-1 effect." (PMID 23028330, 2012). "Activation of MZBs by L. donovani is detrimental to the course of infection, since depletion of MZB results in significantly lower splenic parasite burdens and in stronger CD8 and CD4 T-cell responses." (PMID 21811511, 2012). "No obvious differences were found regarding the numbers of B, T (CD4 and CD8) and NKT cells, between male and female mice before or after infection." (PMID 23028824, 2012). "The analysis of lymphocyte populations from thymus showed the percents (4.5±1.5%) of CD4+CD8+ thymocytes in VK627- and rTsE627K-infected mice were far lower than the percents (82.3±4.3%) observed in rVK627E and TsE627 infection groups at day 5 p.i.." (PMID 22719870, 2012). "Mice treated with anti-CD4 or anti-CD8 antibody at time of infection and 1 day after demonstrated 100% survival up to day 16 post-infection compared to 0% survival for PBS treated FVB mice." (PMID 23300439, 2012). "PHA/IL-2-treated primary human CD4+ T cells exposed to this recombinant reporter virus reached 1.1, 5.8 and 6.6% of HSA-positive cells after 24, 48 and 72 h post-infection, respectively." (PMID 22876188, 2012). "By day 9 post infection the numbers of CD8+ T cells found in IL-10−/− livers were comparable to WT, whereas the numbers of macrophages, CD4+ T cells, and NK cells in these same IL-10−/− livers were still higher as compared to day 9 WT livers." (PMID 22880122, 2012). "HSV-specific CD4+ and CD8+ T cells are expanded following infection, and both populations invade infected skin and contribute to viral clearance." (PMID 22691604, 2012). "Previous reports have shown that following infection with attenuated subspecies of F. tularensis, e.g. LVS, CD4+ and NK cells are primarily responsible for production of IFN-γ in the lung and spleen." (PMID 22428026, 2012). "Specifically, early during experimental murine infection with virulent M. ulcerans, antigen-specific IFN-γ-producing T cells develop in the DLN and differentiated CD4+ cells migrate to the site of infection." (PMID 22413022, 2012). "Of the 492 participants included in this study, the prevalence of recent infections as defined by BED-CEIA test, CD4 counts >200 cells/μl and HIV-RNA >400 copies/mL, was 11.58% (57/492; 95% CI 8.89–14.74)." (PMID 22363755, 2012). "The frequencies of apoptotic CD4+ (%, 29.60±12.58) and CD8+ (43.87±24.97) T cells within each T cell subset were significantly increased during acute phase of infection when compared with healthy controls (CD4+, 15.23±4.39; CD8+, 15.32±4.68)." (PMID 22905277, 2012). "The bacterial pore-forming toxin listeriolysin O (LLO) is paradoxical in that it is cytotoxic at nanomolar concentrations as well as being the source of dominant CD4 and CD8 T cell epitopes following infection with Listeria monocytogenes." (PMID 22403645, 2012). "Percentages of CD4 T cells producing cytokines after first and second H4-IC31-boost and after infection." (PMID 22768165, 2012). "As both CD4 and CD8 IL-7Rα449F T cells showed a dose dependent defect in anti-CD3 induced division, we postulate the route of infection and antigenicity of pathogen challenge can determine the requirement for IL-7R signals." (PMID 23189186, 2012). "Granzyme A was expressed equally in CD4+ and CD8+ which is suggestive of the induction of CTL of both T cell subsets following bTb infection of cattle." (PMID 22359547, 2012). "The ratio of CD4/CD8 cells in yellow cattle and water buffalo pre and post infection with schistosomes were compared and analyzed." (PMID 22414188, 2012). "For example, in the lung, we observe similar, significantly higher numbers of IFN-γ+CD4+ and IFN-γ+CD8+ cells at day 7 and 14 after infection compared to uninfected controls." (PMID 22428026, 2012).